ABCA4 (ATP binding cassette subfamily A member 4)
Diseases named in the same sentence as ABCA4 in open-access papers (continued):
Sharing a sentence is not in itself a finding about the gene and the disease.
Stargardt disease (continued). "Mutations in ABCA4 gene are known to cause Stargardt disease (STGD) which is the most frequent macular dystrophy and typically presents with central macular atrophy and yellow-white dots at the posterior pole, primarily at the level of the RPE." (PMID 29736279, 2018). "Stargardt disease is a juvenile form of autosomal recessive macular degeneration most commonly associated with defects in the ABCA4 gene." (PMID 29229934, 2017). "Affecting approximately 1 in 10,000 individuals, Stargardt disease is an inherited macular degeneration associated with dysfunction in the ATP-binding cassette, subfamily A, member 4 (ABCA4) gene." (PMID 28134823, 2017). "Stargardt Macular Dystrophy: SMD is a retinal degenerative condition caused by mutation in the ATP binding cassette subfamily member 4 (ABCA4; ABCR) gene." (PMID 29326851, 2017). "A highly variable phenotype and progression of some retinal dystrophies, like Stargardt disease, have been documented, and mutations in the ABCA4 gene have also been implicated in cone-rod dystrophy and retinitis pigmentosa." (PMID 28912962, 2017). "It was reported that a portion of patients with the Stargardt disease were bearing single heterozygous mutations in the ABCA4 gene." (PMID 28838317, 2017). "Significantly, the genetic pathogenesis of some previously ambiguous disease phenotypes has also been resolved, most notably the milder, late-onset phenotype of Stargardt disease that is associated with the p.Asn1868Ile ABCA4 mutation." (PMID 29099798, 2017). "The most commonly implicated gene in Stargardt disease was ABCA4, causing recessive Stargardt disease or Fundus Flavimaculatus in 32 pedigrees." (PMID 27624628, 2016). "ABCA4 mutations are the primary cause of Stargardt disease and autosomal-recessive cone-rod dystrophy, in addition to causing a small number of cases of RP9; ABCA4 was therefore the single most commonly implicated gene across all conditions in this study." (PMID 27624628, 2016). "ABCA4 gene mutations are considered among the most common mutations causing RP, cone rod dystrophy, and Stargardt disease." (PMID 26229699, 2015). "An example of this is a recent study of ABCA4 that demonstrated the effect of synonymous mutations and splice site modification mutations as a major cause of Stargardt’s disease." (PMID 26338283, 2015). "Molecular diagnosis of family RP 19 led to the clinical re-evaluation of the family since the identified ABCA4 mutations were previously related to Stargardt disease." (PMID 25544989, 2014). "This study identifes novel compound heterozygous mutations in the ABCA4 gene as a cause of Stargardt’s disease." (PMID 24632595, 2014). "The presence of rare, coding PRPH2 variants in STGD cases with one or more ABCA4 mutations suggests that one must be cautious regarding attributing apparent cases of Stargardt Disease to ABCA4 mutations when only ABCA4 has been screened." (PMID 22863181, 2012). "In family W09–0042, the largest homozygous region contains the ATP-binding cassette, sub-family A, member 4 (ABCA4) gene, which has been associated with Stargardt's disease, cone-rod dystrophy, and to a lesser extent, RP." (PMID 22128245, 2011). "For example, ABCA4 is a member of the ATP-binding cassette transporter sub-family, mutations of which are linked to Stargardt macular dystrophy." (PMID 21711866, 2011). "Occurrence of different typical clinical features of Stargardt disease in patients stratified by the number of discovered ABCA4 mutations." (PMID 20029649, 2009). "The classification of patients suspected of STGD1 into a typical and an atypical STGD1 group (according to our definition) revealed that only 31% of patients with two or three discovered ABCA4 mutations met all typical criteria of Stargardt disease." (PMID 20029649, 2009). "In this study, we identified two novel compound heterozygous mutations, c.655A>T and c.5312+3A>T, in the ABCA4 gene that cause autosomal recessive Stargardt disease in an American family." (PMID 19352439, 2009).
Stargardt disease (continued). "The autosomal recessive form of Stargardt disease (STGD1) is caused by variations in the ATP-binding cassette transporter gene ABCA4 (ABCA4)." (PMID 20029649, 2009). "Genetic disorders of ABCA4 are associated with juvenile onset retinal dystrophies including Stargardt's disease." (PMID 18523590, 2008). "It has been shown that the ABCA4 mutations linked to CRDs are truncating mutations, often on both alleles, whereas amino acid change mutations are more frequently found in Stargardt disease." (PMID 17270046, 2007). "ABCC5 can therefore be added to the list of abundant ABC transporters with a function in the eye which for example includes ABCA4, the gene underlying Stargardt's disease and ABCC6, the gene implicated in pseudoxanthoma elasticum." (PMID 17521428, 2007). "Today, it comprises essentially one gene, ABCA4, which is involved in the retinoid metabolism and causes the Stargardt disease." (PMID 17270046, 2007). "The most notable of these, ABCA4, is involved in vitamin A transport in photoreceptor cells; mutations in the gene encoding ABCA4 can result in a spectrum of retinopathies, including retinitis pigmentosa, Stargardt's disease, cone-rod dystrophy, and ARMD." (PMID 16168081, 2005). "CRB1 (Crumbs Cell Polarity Complex Component 1) mutations, associated with both RP and Leber congenital amaurosis, and ABCA4 (ATP Binding Cassette Subfamily A Member 4) mutations, typically associated with Stargardt disease but also capable of causing RP phenotypes, were also identified." (PMID 41562913, 2026). "Although over 4000 ABCA4 variants have been documented by Clinvar, recent research indicates that additional, previously unidentified disease-associated variants continue to be discovered in individuals with Stargardt disease (STGD1)." (PMID 40244202, 2025). "This variability in disease severity and age of onset can be explained by previous studies, which have reported that biallelic pathogenic variants in the ABCA4 gene are associated with Stargardt disease, typically presenting in the first or second decade of life." (PMID 41465088, 2025). "Additionally, three novel ABCA4 variants were identified in Turkish patients with Stargardt disease, and genotype–phenotype correlations were described." (PMID 41234456, 2025). "Preclinical models such as rd10 mice (a model of RP) and ABCA4-deficient mice (Stargardt disease) serve as critical platforms for evaluating functional efficacy, with optokinetic response testing assessing visual acuity and ERG measuring photoreceptor function." (PMID 40143072, 2025). "For instance, trans modifier genes like ROM1 and PRPH2 may influence the effects of causative ABCA4 variants associated with Stargardt disease." (PMID 39963373, 2025). "Stargardt disease is a currently untreatable, inherited neurodegenerative disease that leads to macular degeneration and blindness due to loss-of-function mutations in the ABCA4 gene." (PMID 39779923, 2025). "Stargardt disease is caused by inheriting biallelic pathogenic variants in the ABCA4 gene." (PMID 40960229, 2025). "Stargardt disease is the primary clinical manifestation associated with ABCA4 variants." (PMID 41465088, 2025). "Finally, although this future therapy is only applicable to a subset of Stargardt disease patients, a substantial number of individuals is expected to benefit from it considering the high prevalence of the ABCA4 c.768G>T variant." (PMID 39838063, 2025). "The most common clinical diagnosis associated with disease-causing variants in ABCA4 is Stargardt disease (STGD1), a juvenile onset macular dystrophy and cone-rod dystrophy, but also cases with cone dystrophy, fundus flavimaculatus and retinitis pigmentosa have been reported." (PMID 40643605, 2025). "Similarly, in a study involving 133 Spanish patients with Stargardt’s disease, 48.1% reported ≥2 mutations and 24.8% reported single mutations in the ABCA4 gene." (PMID 40725253, 2025).
Stargardt disease (continued). "ABCA4 c.1622T>C (p.Leu541Pro) and c.3113C>T (p.Ala1038Val) presented in cis in 2% of patients (n=5/210) and formed a compound heterozygote with another pathogenic or likely pathogenic ABCA4 variant, resulting in Stargardt disease." (PMID 40571344, 2025). "Stargardt disease is an inherited blindness that is caused by defect(s) in the ABCA4 gene." (PMID 39838063, 2025). "Stargardt disease 1, caused by variants in the ABCA4 gene, was the next most prevalent condition." (PMID 41595422, 2025). "It is nearly impossible for patients to distinguish between true diagnostic errors (e.g., mistaking MD/CRD for acquired disorders) and variations in terminology used by different ophthalmologists (e.g., macular dystrophy, Stargardt disease, cone–rod dystrophy, and ABCA4 gene-associated MD/CRD)." (PMID 41302964, 2025). "The patient with Stargardt disease was identified as having ABCA4 variants." (PMID 38307956, 2024). "ABCA4 is responsible for causing over 95% of Stargardt disease 1 (STGD1, MIM #248200)." (PMID 38785568, 2024). "Nowadays, there are three drugs in research pipelines using this approach for ABCA4‐associated Stargardt diseases, dysferlinopathy associated with the DYSF gene, Usher syndrome type 2 B caused by mutations in MYO7A gene and hearing loss due to OTOF malfunction." (PMID 38488469, 2024). "A recent study demonstrated that machine learning techniques could be successfully applied to develop automated ERG phenotypic classification of patients with Stargardt disease (arising from variants in the ABCA4 gene)." (PMID 36928229, 2023). "In Stargardt’s disease caused by mutations resulting in the loss of function in ATP-binding cassette transporter subfamily A member 4 (ABCA4), the removal of retinaldehydes from phagocytosed tips of POS can be further compromised, thereby increasing the risk of its oxidation." (PMID 38203675, 2023). "Missense variants in ABCA4 constitute ~50% of causal variants in Stargardt disease (STGD1)." (PMID 37555651, 2023). "The ABCA4 gene that codes for subfamily A, ATP-binding cassette, and member 4 transporter system undergo biallelic mutations resulting in pathogenicity in the retina that manifests as Stargardt disease." (PMID 36836473, 2023). "Stargardt disease (STGD1, OMIM# 248200), also known as fundus flavimaculatus or ABCA4-retinopathy, is the most frequent retinal dystrophy caused by a single gene, characterized by a progressive degeneration of the retinal pigment epithelium (RPE) and photoreceptors." (PMID 36833218, 2023). "Interestingly, the second variant (c.1555:2745A>G) was detected along with the first variant (c.5196+1137G>A) and another variant (p.C54Y) in the same gene (ABCA4) in a patient affected with Stargardt disease." (PMID 36833373, 2023). "Pseudodominant inheritance has already been documented in retinal disorders, including congenital stationary night blindness (CSNB) with alterations in the GRM6 gene, in patients with RP related to IMPG2 variants, or in cone-rod dystrophy and Stargardt disease with ABCA4 pathogenic variants." (PMID 36832217, 2023). "Furthermore, our investigation revealed that patients with loss-of-function variants in ABCA4 were more inclined to develop phenotypes distinct from Stargardt disease." (PMID 38003421, 2023). "Stargardt disease (STGD1), also known as fundus flavimaculatus or ABCA4-retinopathy, is a progressive disorder of the retina caused by bi-allelic variants in the gene that encodes ATP-binding cassette subfamily A member 4 (ABCA4), localized on chromosome 1p22.1." (PMID 35162940, 2022). "Deep intronic variants in ABCA4 are also frequently observed in Stargardt disease." (PMID 35457110, 2022). "For example, Stargardt disease is predominantly caused by biallelic variants in ABCA4 gene." (PMID 35911417, 2022).
Stargardt disease (continued). "Although recent studies have deciphered most of the genetic variation underlying ABCA4/Stargardt disease, including non-coding variants and cis-modifiers in the ABCA4 locus, many causal and modifying variants are still unknown." (PMID 35353811, 2022). "Bi-allelic mutations in ABCA4 are responsible for various forms of recessive retinal dystrophies, including Stargardt disease (STGD1), while heterozygous mutations can increase disease risk or lead to later disease onset compared to bi-allelic mutation carriers." (PMID 35361255, 2022). "Stargardt’s disease (STGD1) is caused by mutations in the ABCA4 gene." (PMID 35330133, 2022). "Other viral vectors such as lentiviral vectors have been used for some autosomal recessive disorder to deliver cDNA copies of the mutant genes that are too large to be carried by AAV, e.g., ABCA4 gene associated with Stargardt disease and MYO7A associated with Usher’s syndrome." (PMID 35911417, 2022). "In addition, pathogenic deep-intronic variants in ABCA4 are found to contribute to the recessive inheritance of Stargardt disease." (PMID 35361255, 2022). "In particular, the H3 haplotype reduced promoter activity; therefore, investigating whether this haplotype is associated with the ABCA4-associated retinopathy, including Stargardt disease, through presenting with other ABCA4 variants, is necessary." (PMID 36566289, 2022). "In addition, some introns seem more prone to harbor disease-causing mutations than others, as observed in the ABCA4 gene in which the clustering in certain introns of deep-intronic variants causing Stargardt disease has been reported." (PMID 35833796, 2022). "A prominent example is Abca4, which encodes a membrane flippase that transports vitamin A retinal-lipid adducts in the photoreceptor outer segment and is clinically associated with a form of Stargardt macular dystrophy." (PMID 36142331, 2022). "This study revealed that several ABCA4 variants found in patients with Stargardt disease could affect ABCA4 expression, and common variants of the ABCA4 proximal promoter alter the ABCA4 transcriptional activity, which is regulated by GATA-2 and HLF." (PMID 36566289, 2022). "Mutations in the ABCA4 gene are a known cause for recessive Stargardt disease (STGD1)." (PMID 34945039, 2021). "Stargardt Disease can result from many hundreds of different mutations in ABCA4 or other genes." (PMID 33546345, 2021). "In addition, mutations in ABCA4, an ATP-binding cassette transporter facilitating the removal of potentially reactive retinal lipid derivatives, have been implicated in Stargardt's disease pathology." (PMID 33465374, 2021). "In the case of Stargardt disease, a large proportion of mutations in ABCA4, ELOVL4 and PROM1 could be targeted with one or more of the currently described CRISPR-based approaches: genome editing, epigenetic repression, base editing or prime editing." (PMID 34439845, 2021). "Stargardt disease is predominately caused by biallelic variants in the ABCA4 gene." (PMID 34073611, 2021). "In this retrospective, observational study, we characterize the thicknesses of individual retinal sublayers by macular optical coherence tomography (OCT) in a large cohort of patients with molecularly-confirmed, ABCA4-associated Stargardt disease (STGD1) relative to normal controls." (PMID 33024232, 2020). "The mutant variants in ABCA4 are mainly responsible for autosomal recessive retinal dystrophies, including Stargardt disease (STGD1; OMIM 248200), retinitis pigmentosa (RP19; OMIM 601718), cone-rod dystrophy (CRD3; OMIM 604116), and early-onset severe retinal dystrophy (OMIM 248200)." (PMID 33129279, 2020). "Stargardt disease is produced by a mutation in the ABCA4 gene." (PMID 33066661, 2020). "Unfortunately, to date, the pathogenicity of many ABCA4 variants remains unclear, and some supposedly deleterious variants may influence the onset of Stargardt disease in different ways." (PMID 32413971, 2020).
Stargardt disease (continued). "Interestingly, a proportion of recessive RP pedigrees (>9%) (7/71) carry variants in ABCA4, typically associated with Stargardt Disease, a form of macular dystrophy." (PMID 31963381, 2020). "Additionally, using hair follicles from patients with Stargardt disease, we investigated the molecular consequences of selected ABCA4 variants on gene processing." (PMID 32413971, 2020). "ABCA4 mutations can result in multiple vision related phenotypes including Retinitis pigmentosa, Fundus flavimaculatus, Cone-rod dystrophy, and Stargardt disease, which is characterized by juvenile macular degeneration." (PMID 30245926, 2018). "As it has previously been noted the main differential diagnostic of HJMD from an ophthalmological point of view is not only Stargardt’s disease, which is caused mainly by ABCA4 mutations, but any retinal dystrophy phenotype suggestive of CDH3, regardless of the hair phenotype." (PMID 28061825, 2017). "Clinical features of Stargardt disease probands with the ABCA4 mutations identified in this study." (PMID 26161775, 2015). "The ABCA4 causative variants in 19 Chinese probands with Stargardt disease." (PMID 26161775, 2015). "Our findings provide one novel ABCA4 mutation in Chinese patients with Stargardt disease." (PMID 24632595, 2014). "Misfolding and ER retention of other lipid ABC transporters of the A subfamily, as ABCA1 and ABCA4, cause Tangier disease and Stargardt macular dystrophy, respectively, but their influence on ER stress and apoptosis is unknown." (PMID 21214890, 2011). "Mutations in ABCA4 are responsible for almost all cases of classic Stargardt disease." (PMID 19352439, 2009). "The diversity of phenotypes, ranging from inherited retinal dystrophies (such as Stargardt disease 1, cone–rod dystrophy 3, and retinitis pigmentosa 19) to late-onset age-related macular degeneration 2, has been attributed to loss-of-function variants in the ABCA4 gene." (PMID 40606666, 2025). "The early onset and rapidly progressing vision loss (with light perception in the left eye and no light perception in the right eye), which is incompatible with USH2C, may be explained by an additional homozygous variant c.4919G>A p.(Arg1640Gln) in ABCA4, which causes Stargardt disease." (PMID 34148116, 2022). "The Abca4 gene and corresponding protein have recently been shown to be expressed both in photoreceptors and in the RPE, which may yield new avenues for understanding ocular vitamin A metabolism and interpreting the effect of ABCA4 mutations in Stargardt disease." (PMID 36142331, 2022). "Subsequent Sanger sequencing of the ABCA4 Stargardt disease gene, located on chromosome 1, uncovered a homozygous pathogenic deep intronic variant (Chr1(GRCh37):g.94546780C>G NM_000350.2(ABCA4):c.859‐506G>C) leading to a pseudo‐exon in a substantial proportion of the ABCA4 transcripts." (PMID 35191116, 2022). "Furthermore, CK30PEG containing the large ABCA4 cDNA cassette (6.8 kb) was able to drive sustained expression for up to eight months after injection and to improve the phenotype of an Abca4-deficient Stargardt disease mouse model when delivered subretinally." (PMID 33652562, 2021). "Stargardt disease has a highly variable phenotype but there are three characteristic features: the presence of flecks, macular atrophy, and sparing of the peripapillary region, which if seen together are indicative of a retinal disorder associated with variants in ABCA4.." (PMID 34440414, 2021). "To assess whether hair follicles are a suitable source of material for the study of the consequences of ABCA4 mutations, we analyzed hair follicle-derived mRNA obtained from patients with Stargardt disease carrying representative c.5312+1G>A, c.5312+2T>G and c.5836-3C>A ABCA4 variants." (PMID 32413971, 2020). "Insufficiency of ABCA4, as observed in Stargardt’s disease, leads to the accumulation of NRPE in the outer segment of photoreceptors." (PMID 40725253, 2025).